TNF (tumor necrosis factor)
Diseases named in the same sentence as TNF in open-access papers (continued):
Sharing a sentence is not in itself a finding about the gene and the disease.
gastric cancer (continued). "Another study reinforced PTX3’s role in promoting migration of gastric cancer cells and identified its ability to recruit macrophages through TNF-α/NF-κB activation-driven PTX3 upregulation." (PMID 41479916, 2025). "In gastric cancer, TNF-α contributes to angiogenesis, immune suppression, and cancer cell migration." (PMID 40255569, 2025). "It would be valuable to follow gastric cancer patients over time to see if baseline or postoperative TNF-α levels predict outcomes like recurrence-free survival or overall survival." (PMID 40299527, 2025). "In gastric cancer liver metastases, NK cells showed reduced expression of IFNγ and TNF, partially driven by TGFβ-mediated suppression." (PMID 40621458, 2025). "We expand on that concept by demonstrating that TNF-α is also meaningfully linked with CA19-9 and CA72-4, which are critical markers for gastric cancer monitoring." (PMID 40299527, 2025). "For example, in vitro experiments have shown that exposing gastric cancer cells to TNF-α enhances their invasive potential by downregulating protective factors like pentraxin-3." (PMID 40299527, 2025). "In gastric cancer, TNF-α can activate NF-κB and other pathways that lead to cancer cell proliferation, survival, and angiogenesis." (PMID 40299527, 2025). "In patients with gastric cancer at stage IV of the disease, multidirectional changes occur when studying proinflammatory cytokines: a decrease in TNF-α, IL-8, TNF-β, as well as an increase in IL-2, IFNγ, IL-17A, and IL-6." (PMID 40806737, 2025). "From a biological standpoint, the prominent association of TNF-α with tumor markers and advanced disease in gastric cancer can be contextualized by TNF-α’s known roles in cancer biology." (PMID 40299527, 2025). "In conclusion, our study demonstrates that TNF-α levels are significantly elevated in gastric cancer patients and closely correlate with key tumor markers (especially CA19-9 and CA72-4), reflecting the tumor burden and aggressiveness of the disease." (PMID 40299527, 2025). "TNF‐α is a key marker for assessing the prognosis of gastric cancer patients, while IL‐6 enhances AGS cell invasiveness, contributing to metastatic progression." (PMID 40838679, 2025). "In gastric cancer, TNF-α exhibits a dual nature: it can promote tumor progression through angiogenesis, cellular proliferation, and infiltration, while also possessing the capacity to induce apoptosis under specific conditions." (PMID 40299527, 2025). "Tα1 increased the percentage of CD4+CD25+Foxp3+ (suppressive antitumor-specific Tregs), Tregs, IL-1β, TNF-α, and IL-6 in patients with gastric carcinoma." (PMID 40599771, 2025). "TNF-α is also involved in resistance to anticancer therapy, as evidenced by the decreased sensitivity of gastric cancer to trastuzumab following TNF-α exposure." (PMID 38520006, 2024). "Administration of cytokine (IL-1, IL-6, IL-18, TNF) antagonists is the other therapy for gastric cancer patients." (PMID 39003350, 2024). "Atractylenolide I improves the malignant quality of tumor patients, and atractylenolide I treatment increases body weight, appetite, KPS score, and TNF-α level in gastric cancer patients." (PMID 39479020, 2024). "S. bovis infection not only advances colorectal cancer by recruiting CD11b+TLR-4+ cells and releasing inflammatory cytokines (IL-6, IL-1ß and TNF), but also boosts gastric cancer by affecting immune cells (CD3+ T cells and NK cells) in the peripheral blood." (PMID 38774627, 2024). "Inflammatory cytokines such as IL-1, IL-6, and TNF-α involve in the gastric cancer-related inflammation." (PMID 38444674, 2024). "The secondary outcomes were the expression levels of TLR4 (Toll-like receptor), IL-6 and TNF-α in gastric cancer tissue." (PMID 38720250, 2024). "In gastric cancer cells, KIAA1429 tends to regulate immune-associated pathways, and the TNF (tumor necrosis factor) signaling pathway is the pathway most affected by KIAA1429." (PMID 39456252, 2024).
gastric cancer (continued). "CD204+ M2-like TAMs can utilize the TNF-α/NF-κB/HIF-1α/miR-210/NTN4 pathway to facilitate gastric cancer progression." (PMID 38175202, 2024). "PD‐L1 gene expression is regulated by the inflammatory cytokines TNF‐α and IL‐6 secreted by infiltrated macrophages in gastric cancer." (PMID 38660687, 2024). "Research indicates that TNF-α derived from gastric cancer induces the production of CD45RA−CCR7+ Treg subsets by activating STAT3 phosphorylation." (PMID 39840050, 2024). "Other studies on gastric cancer have shown that the release of TNF‐α and IL‐6 activates NF‐κB signaling and upregulates PD‐L1 expression in tumor cells, consequently promoting the immune escape of tumor cells." (PMID 38660687, 2024). "Research suggests that the early introduction of EIN after surgery curtails CRP and TNF-αsynthesis, markedly enhancing immune responsiveness and suppressing inflammation in patients with gastric cancer." (PMID 37960219, 2023). "In terms of inhibition of cell viability, we observed contradictory effects of HDGF and TNFα on 3-D human gastric cancer organoids that were infected with CagA-GFP-Hp0549." (PMID 37047540, 2023). "Some scholars believe that PADI4 promotes the occurrence and development of gastric cancer by up-regulating TNF-α, CXCR2, and KRT14 in MNK-45 cells and SGC 7901 cells." (PMID 37804426, 2023). "Then, using the network pharmacology method, the proliferation of gastric cancer was inhibited by the oridonin through 11 signalling pathways, among which TNF‐α, AR and TGF‐β signalling pathways were the three most important signalling pathways." (PMID 37431884, 2023). "IL-6 and TNF-α were the only cytokines presenting a significant increase upon both H. pylori infection and gastric cancer development." (PMID 37006300, 2023). "Chronic inflammation measured based on TNF-a, CRP, and IL-6, among others, is highly correlated with an increased risk of gastric cancer; those measurements can be practical in predicting gastric cancer development at very early stages." (PMID 38068839, 2023). "To clarify the role of HDGF and TNFα secreted from H. pylori-infected cancer organoids, we prepared recombinant HDGF and TNFα and measured the cytotoxicity and invasion of gastric cancer organoids." (PMID 37047540, 2023). "In contrast, it has been reported that RACK1 is a negative regulator of NF-κB signalling in TNF-α-treated 293T cells, classical swine fever virus-infected PK-15 cells and Helicobacter pylori-infected gastric cancer cells." (PMID 37684678, 2023). "Recombinant HDGF and TNFα inhibited the growth and invasion activities in 3-D-gastric cancer organoids." (PMID 37047540, 2023). "According to one study, increased intratumoral mast cells promoted immune suppression and gastric cancer growth through the TNF-PD-L1 pathway." (PMID 36793271, 2023). "This study mainly aimed to investigate the role of TNF‐alpha/Androgen receptor/TGF‐beta signalling pathway axis in mediating the proliferation inhibition of oridonin on gastric cancer SGC‐7901 cells." (PMID 37431884, 2023). "While TNFα is defined as the upstream partner of HDGF in 2-D gastric cancer cells, in 3-D organoids in culture, HDGF and TNFα are independent signals for development of H. pylori-infected gastric cancer." (PMID 37047540, 2023). "Further studies are required to examine the roles of both HDGF and TNFα in organoid viability and invasion capacity for gastric cancer progression and to identify the signaling pathways in H. pylori infection." (PMID 37047540, 2023). "Recombinant HDGF and TNFα inhibited the development and invasion of H. pylori-infected gastric cancer differently." (PMID 37047540, 2023). "Previously, we reported that HGDF and TNFα were crucial for cancer initiation and development using two-dimensional (2-D)-gastric cancer cell lines." (PMID 37047540, 2023).
gastric cancer (continued). "In a more specific tumoral context, lncH19 has been shown to participate in triptolide/TNF-α-induced apoptosis via binding miR-204-5p in gastric cancer models." (PMID 37841928, 2023). "In gastric cancer, mast cells promote immunosuppression and progression of gastric cancer through the TNF-α-PD-L1 pathway." (PMID 36018370, 2023). "EVs from gastric cancer(GC) cells treated with MLT promote the expression of TNF-α and CXCL10 in macrophages while suppressing IL-6 and MCP-1 expression, concurrently downregulating PD-L1 protein levels." (PMID 38087360, 2023). "Western blot assay was adopted to verify the TNF‐α/Androgen receptor/TGF‐β signalling pathway axis regulation on gastric cancer by oridonin." (PMID 37431884, 2023). "TNF-α exerts many biological effects, from cell proliferation to cell death, and is involved in tumor initiation and progression, including gastric cancer and ovarian cancer." (PMID 37233761, 2023). "Tumour necrosis factor (TNF)-α plays an important role in inflammatory, infectious, and tumor processes, and it is closely related to the early stages of gastric cancer." (PMID 35186129, 2022). "It has been reported that TNF-α, an inflammatory cytokine secreted from macrophages, promotes cancer cell proliferation, migration, and invasion in gastric cancer, colon cancer, breast cancer, and kidney cancer." (PMID 36613819, 2022). "TNF alpha protein specifically binds to cell-surface nucleolin and then enters the gastric cancer cells, where TNF-a and chemokine gene expressions are induced by NF-jB activation." (PMID 35186129, 2022). "Aside from its implications in peptic ulcers and gastric cancer, TNF-α seems to also play a role in the etiology of other human disorders, such as Alzheimer’s disease, major depression, non-gastric cancers or inflammatory bowel disease." (PMID 35884067, 2022). "Our experimental design for the first time depicted that H19 is the upstream member of NF-κB signaling in gastric cancer cells upon TNF-α stimulation." (PMID 36110523, 2022). "The induction of apoptosis is related to BAX overexpression, BCL-2 downregulation, and inhibition of inflammation, as revealed by the downregulation of IL-6, TNF-α, IL-1β, and IL-8 which modulate cell growth proteins in gastric cancer cells." (PMID 36359261, 2022). "PTX-3 overexpression, infiltration of CD11b+ macrophages, TNF-α, and NF-ƙB activation were noted in human advanced gastric cancer tissues and contributed to gastric cancer-related inflammation." (PMID 36499628, 2022). "Infection by Helicobacter pylori induces inflammation in the stomach microenvironment and is associated with the induction of cytokines, such as tumor necrosis factor-α (TNF-α), interleukin-1β, and interleukin-6, which lead to gastric cancer." (PMID 36613819, 2022). "Similar in another study, GAS5 promoted the secretion of IFN-γ and TNF-α by regulating miR-18a, thereby enhancing the killing effect of NK cells on gastric cancer (GC)." (PMID 35222443, 2022). "Inflammatory cytokines that support gastric cancer-related inflammation include IL-1, IL-6, IL-18, TNF-α, and TGF-β." (PMID 35892729, 2022). "TCP-1, a peptide targeting the vasculature of gastric cancer cells, was conjugated to tumor necrosis factor α (TNFα) to deliver the anticancer agent 5-fluorouracil (5-FU)." (PMID 35744930, 2022). "To further examine the anti-apoptosis mechanism of the volatile oil of R. rubescens in gastric cancer cells, we performed western blotting to detect the four core targets, TNF, IL1B, MPP9 and PTGS2." (PMID 36200190, 2022). "Increased expression of tumor-related inflammatory mediators and cytokines, such as tumor necrosis factor-α, interleukin-1 (IL-1), and IL-6, have been reported to be increased in gastric cancer cases and other cancers." (PMID 36387250, 2022). "In this study, we have verified that TNF-α secreted from macrophages promotes cancer metastasis by increasing integrin αV expression in gastric cancer cells." (PMID 36613819, 2022).
gastric cancer (continued). "Our study confirmed that the secretion of TNF-α by macrophages promotes the metastasis of gastric cancer cells, thereby providing a basis for the use of TNF/TNFR inhibitors for the development of gastric cancer treatment agents." (PMID 36613819, 2022). "miRNA-204 leads to enhanced BIRC2 expression level and BIRC2/TNF-a/NF-kB signaling pathway activities, which promoted angiogenesis and metastasis of gastric cancer cells." (PMID 36314013, 2022). "TNF alpha is the most studied marker in gastric cancer, and it has been shown that at the cellular level, its polymorphism is of particular importance as the gene is identified at the level of chromosome 6." (PMID 35186129, 2022). "In gastric cancer, elevated intratumoral mast cells resulted in immune suppression via modulating TNF-α-PD-L1 pathway." (PMID 35140786, 2022). "The tumor necrosis factor TNFαlpha plays an important role in the process of inflammation, infection, and tumors and has central importance in the early stages of gastric cancer." (PMID 35186129, 2022). "We demonstrated the regulation of integrin αV expression through the TNF-α–ERK–VGLL1–TEAD4 pathway in the coculture of gastric cancer cells with macrophages cells." (PMID 36613819, 2022). "In contrast, TNF-α is decreased in H. pylori-infected gastric cancer patients, and it has been proposed that this cytokine is involved in early stages of gastric carcinogenesis." (PMID 35955936, 2022). "But in the other clinical study involving 71 operative gastric cancer cases, preoperative high TNFα indicated better outcomes." (PMID 35859928, 2022). "RANK-L, which belongs to the tumor necrosis factor (TNF) family, can be secreted not only by bone-related cells but also by infiltrating T cells, which are abundant in gastric cancer." (PMID 36230816, 2022). "Our laboratory has found that LPS induces ILK-dependent phosphorylation of Akt and GSK3β, as well as phosphorylation of NF-κB p65 at Ser536 and TNF-α production in gastric cancer cells." (PMID 34163519, 2021). "In patients with gastric cancer, exosomal TNF-α and TGF-β levels were increased, whereas the IL-10 level was decreased." (PMID 33803292, 2021). "In epithelial cells of gastric cancer and gastritis, TNF-α stimuli upregulate NOX1 and the inhibition of NF-κB/P65 by shRNA remarkably blocked the upregulation of NOXO1, which is one component forming NOX1." (PMID 33757467, 2021). "Tipα secreted from H. pylori stimulates gastric cancer development by inducing TNF-α, an endogenous tumor promoter, through its interaction with nucleolin, a Tipα receptor." (PMID 33804551, 2021). "NADPH oxidase 1 (NOX1)-induced reactive oxygen species (ROS) signaling contributes to gastric cancer development and stemness through effects on the TNFα/NF-κB pathway." (PMID 33406733, 2021). "TNFα secreted from gastric cancer cells induces PD-L1 expression in mast cells via activation of the NF-κB signaling pathway." (PMID 33540543, 2021). "Ginger extract 6-gingerol has been proved to induce the apoptosis of gastric cancer cells through tumor necrosis factor (TNF)-related apoptosis-inducing ligand-(TRAIL-)." (PMID 33692694, 2021). "Decreased cell membrane receptor-bound TNFα was detected in gastric cancer cells transfected with ADAM17-shRNA." (PMID 34182543, 2021). "TNF-α-induced MMP-9 secretion from mesothelial cells plays an important role in the metastatic dissemination of gastric cancer." (PMID 34016788, 2021). "In the case of gastric cancer, the HER2 expressing gastric cancer cell line sensitive to trastuzumab NCI-N87 becomes refractory to the antibody after TNFα exposure." (PMID 33540543, 2021). "Gastric cancer cells in turn, secrete TNF-α to induce the release of CXCR2 ligands from macrophages." (PMID 34012923, 2021). "A direct correlation was demonstrated between PD-L1+ mast cells and TNFα in gastric cancer specimens." (PMID 33540543, 2021).
gastric cancer (continued). "rTipα induced the expression of IL-1β, IL-8, and TNF-α to higher levels in the human gastric cancer cell line SGC7901 than in the human gastric epithelial cell line GES-1." (PMID 33804551, 2021). "In a follow-up study the same researchers demonstrated that the invasiveness of gastric carcinoma-derived cancer cells was promoted by tumor necrosis factor (TNF)-α released from macrophages in a fibrinogen-dependent manner." (PMID 33466303, 2021). "TNF-a plays an important role in gastric carcinoma through the activation of the Wnt/β​​​​​​-catenin signaling pathway." (PMID 34168929, 2021). "Macrophages release TNF-a which promotes the upregulation of the Wnt/β​​​​​​-catenin signaling, therefore contributing to gastric carcinoma development." (PMID 34168929, 2021). "Conversely, overexpression of PTX3 inhibited progress both in vitro as well as in vivo in gastric cancer mediated by TNF-α." (PMID 32194791, 2020). "In order to explain the role of TNF-α on PTX3 in the migration as well as invasion of gastric cancer cells, we performed transwell assays." (PMID 32194791, 2020). "Tumor necrosis factor (TNF-α) is an imperative cytokine that demonstrates an extensive array of biological consequences in gastric cancer advancement." (PMID 32194791, 2020). "SLFN12L+ myeloid cells express VEGF, IL-1β and TNF-α, which are known factors associated with MDSC regulation, an immunosuppressive cell of relevance to immunotherapy-resistant gastric cancer." (PMID 33348809, 2020). "To identify the mechanism of PTX3 on the process of EMT of gastric cancer cells mediated by TNF-α, we examined typical EMT markers by western blot." (PMID 32194791, 2020). "Knockout of TXNIP can promote the development of gastric cancer induced by Helicobacter pylori in C57BL/6 mice by inhibiting the induction of tumor necrosis factor (TNF-α), nuclear factor kappa-B (NF-κB), and cyclooxygenase-2 (COX-2)." (PMID 33194655, 2020). "We established that upregulation of PTX3 noticeably reduced the gastric carcinoma migration and invasion capacity mediated by TNF-α." (PMID 32194791, 2020). "Reportedly, TNFα/CHX induced apoptosis in gastric cancer cells MKN28, which was triggered by accelerated degradation of IAP family proteins in addition to inhibition of the NF-kB-dependent synthesis of antiapoptotic molecules." (PMID 31637258, 2019). "On the other hand, it has been also reported that gastric cancer-derived exosomes activate the NF-kB pathway in recipient macrophages, leading to up-regulation of pro-inflammatory factors such as IL-6 and TNF-α which promote gastric cancer progression." (PMID 31686989, 2019). "The best model wasobtained with the highest scoring template (PDB id: 2wcr) whichstands for Tip-α protein that induces expression of TNF-α in B celland promotes tumor activities and thus results in gastric cancer." (PMID 31485131, 2019). "Gastric cancer-derived exosomes induced NF-kB activation in macrophages, leading to an increase in the expression of pro-inflammatory factors such as IL-6 and TNF-a, in turn promoting the proliferation of gastric cancer cells." (PMID 30987213, 2019). "We previously reported that Noxo1 expression is induced in gastric tumors by TNF-α signaling and is important for the maintenance of tumorigenicity of human stomach cancer cells." (PMID 30700829, 2019). "For instance, gastric cancer-derived exosomes were shown to induce NF-κB activation in macrophages, leading to an increase in the expression of pro-inflammatory factors such as IL-6 and TNF-α, in turn promoting the proliferation of gastric cancer cells." (PMID 29515996, 2018). "For example, TNF-α treatment of human gastric cancer cells was shown to increase MMP-9 mRNA and protein expression levels." (PMID 30544870, 2018). "Previous studies reported that NF-κB activation in macrophages increase the expression of cytokines such as TNF-α and IL-6, in turn promoting the proliferation of gastric cancer cells." (PMID 30266897, 2018).